NAA80 (N-alpha-acetyltransferase 80, NatH catalytic subunit)
Description:
N-alpha-acetyltransferase that specifically mediates the acetylation of the acidic amino terminus of processed forms of beta- and gamma-actin (ACTB and ACTG, respectively). N-terminal acetylation of processed beta- and gamma-actin regulates actin filament depolymerization and elongation. In vivo, preferentially displays N-terminal acetyltransferase activity towards acid N-terminal sequences starting with Asp-Asp-Asp and Glu-Glu-Glu. In vitro, shows high activity towards Met-Asp-Glu-Leu and Met-Asp-Asp-Asp. May act as a tumor suppressor.
Synonyms: HsNAAA80; FUS2; NAT6; ANDS; FUS-2
Tractability: Small molecule: a structure with a bound ligand is known.
Gene: Protein-coding gene on chromosome 3 (50,296,402 to 50,299,416, reverse strand). Ensembl gene ENSG00000243477.
Subcellular location: Cytoplasm, cytosol
Gene Ontology:
Molecular function: acetyl-CoA binding; N-acetyltransferase activity; protein-N-terminal amino-acid acetyltransferase activity; acyltransferase activity, transferring groups other than amino-acyl groups
Biological process: actin modification; N-terminal peptidyl-aspartic acid acetylation; N-terminal peptidyl-glutamic acid acetylation; protein acetylation; regulation of actin polymerization or depolymerization
Cellular component: cytoplasm; cytosol
Genetic constraint (gnomAD): Loss-of-function variants: 6 observed, 10.54 expected, observed/expected ratio (o/e) 0.57, 90% interval 0.31 to 1.12. The upper end of that interval is the gene's LOEUF score, 1.12, which puts it in group 4 of 6, group 1 being the genes least tolerant of losing a copy. Missense variants: 360 observed, 364.59 expected, observed/expected ratio (o/e) 0.99, 90% interval 0.9 to 1.08. Synonymous variants: 149 observed, 155.11 expected, observed/expected ratio (o/e) 0.96, 90% interval 0.84 to 1.1.
Homologues: Orthologues: chimpanzee NAA80 (98% identical), macaque NAA80 (97% identical), rabbit NAA80 (78% identical), rat Naa80 (76% identical), mouse Naa80 (76% identical), pig NAA80 (72% identical), guinea pig NAA80 (53% identical), zebrafish naa80 (36% identical), tropical clawed frog naa80 (36% identical), Caenorhabditis elegans C56G2.15 (23% identical), Drosophila melanogaster Naa80 (19% identical).
Diseases named in the same sentence as NAA80 in open-access papers:
NAA80 is named in the same sentence as 6 diseases in open-access papers, as found by Europe PMC text mining. Sharing a sentence is not in itself a finding about the gene and the disease. The quoted sentences say what the papers report.
glioblastoma (1 paper, 2020). The most malignant astrocytic tumor (WHO grade IV). "However, in another published study comparing normal with glioblastoma tissues, NAA30 and NAA80, which are associated with improved survival are downregulated, while NAA15, which is associated with worse survival, is upregulated." (PMID 32942614, 2020).
hearing loss (1 paper, 2021). "As NAA80-mediated actin acetylation results in altered actin dynamics, it is likely that normal cytoskeletal architecture is disrupted in NAA80 patients, causing hearing loss." (PMID 34805998, 2021).
intellectual disabilities (1 paper, 2024). "Further, a recent human genetic study associated mutations in NAA80, which encodes an enzyme specific for N-acetylation of actin, among others with actin dysregulation, brain developmental defects and intellectual disabilities." (PMID 39154297, 2024).
cancer (1 paper, 2020). A tumor composed of atypical neoplastic, often pleomorphic cells that invade other tissues. "Within the DepMap genome-wide CRISPR knockout (KO) screen consisting of 739 cell lines of diverse tissue origin, most NATs were essential to all or to a subset of cancer cells, with the exception of NAA60, NAA80, NAA38, NAA11 and NAA16." (PMID 32942614, 2020).
NAA80 also shares sentences with these, for which no sentence is quoted: developmental delay (1 paper); neurodevelopmental disorder (1).